DCX (doublecortin)
Diseases named in the same sentence as DCX in open-access papers (continued):
Sharing a sentence is not in itself a finding about the gene and the disease.
cancer (continued). "It is predictable that the importance of DCX in cancer cells will be further appreciated with a wide interest in its research by scientists from different fields and the development of new therapeutic agents directed against the cytoskeleton to curb the development of cancer cells." (PMID 28701917, 2017). "Moreover, phosphatase and tensin homolog (PTEN), an antioncogene often expressed in human cancer act on DCX." (PMID 28701917, 2017). "There are existing studies suggesting that the expression of DCX may relatively be considered in cancer prognosis and survival rate." (PMID 28701917, 2017). "When DCX is phosphorylated, MTs unbundles and depolymerization sets in, a process that may be adopted by migrating cancer cells, taking advantage of the destabilized MT network to invade its surrounding cells." (PMID 28701917, 2017). "Perhaps these phosphorylations may be required to initiate and maintain uncontrolled movement of cancer cells due to the destabilization of the MTs, as uncooperative MT stapling and aversion for MT tips may explain DCX involvement in the movement of invasive cancer cells." (PMID 28701917, 2017). "Cluster 7 included cells with aberrant neuronal identity that expressed neuronal development genes (NEFM, DCX, STMN2, HES6) but also cell cycle and cancer-related genes (CRABP2, CCND1, MYC)." (PMID 33771987, 2021). "Cells in cluster 5 resembled those in cluster 7 of DNs, and included cells with aberrant neuronal identity that expressed neuronal genes (GAP43, NEFM, DCX, HES6) and cancer-related proliferative genes (CRABP1, MYC, SFRP1)." (PMID 33771987, 2021). "DCX is a neuronal MAP that is crucial to the migration of neuroblasts, and this makes it a vulnerable target for cancer cells." (PMID 28701917, 2017). "As GBM1 tumors contain undifferentiated SVZ cells including DCX-positive neuroblasts, we further showed that c-Myc is abundant in the DCX-positive population in GBM1 specimen, offering a specific protein expression profile for the putative cancer initiating cells." (PMID 23875172, 2013). "Unlike DCX mRNA, LIS1 mRNA was present in cancers of non-NE origin and MES-type cells, which could reflect LIS1 function during spindle assembly." (PMID 33658318, 2021). "Herein, we showed that the i.c.v. administration of histamine does not induce a significant increase in the total number of BrdU+DCX- or Ki67+DCX- cells at the SVZ, suggesting that, at least after 21 days, histamine does not induce a cancer-like profile of SVZ NSCs cells in vivo." (PMID 24982610, 2014).
infection (19 papers, 2011 to 2025). The state of being infected such as from the introduction of a foreign agent such as serum, vaccine, antigenic substance or organism. "ShRGMa infection caused a significant increase of DCX+ cells in the dentate gyrus compared with shNT infection (p = 0.0088)." (PMID 32243839, 2020). "To investigate the impact of TMEV infection on neuronal progenitor proliferation, we conducted a focused analysis on the percentage of double-stained DCX+/KI-67+ cells." (PMID 39876841, 2024). "At 3 dpi, despite very few DCX+ cells remaining after infection, a discernible aberration in the migratory behavior of DCX+ cells was evident: 50% of the detectable DCX+ cells exhibited a migration score 4 in TMEV-infected mice." (PMID 39876841, 2024). "The proportion of GFP+DCX+ to GFP+ cells indicated that neuron development was directly promoted by AAV-β-catenin infection (cKO-β-catenin 12.34% vs. cKO-GFP 2.33%, P < 0.05), thus implying its autocrine effect." (PMID 35410459, 2022). "Consistent with glia-to-neuron fate conversion, the acquisition of mature neuronal traits was progressive as illustrated by the initial expression of the immature neuronal marker DCX in iNs at 10 days post-infection (dpi)." (PMID 34592167, 2021). "This prompted us to further investigate both mRNA and protein levels of DCX throughout a longer infection time course." (PMID 29922247, 2018). "Further validation of proliferation arrest in neuronal precursor cells and reduced DCX expression with progressive infection was obtained from decreased expression of neurotrophins, such as BDNF and NT3." (PMID 21249143, 2011). "In addition, co-localization with DCX confirmed infection of immature neurons, particularly in the SVZ and lateral ventricle." (PMID 40743437, 2025). "This decline in DCX+ cells persisted up to 7 weeks post-infection." (PMID 39876841, 2024). "Next, we sought to elucidate the impact of TMEV infection on DG neuronal progenitors (DCX+)." (PMID 39876841, 2024). "Interestingly, some DCX+ neurons were observed in the hilar region of the dentate gyrus after shRGMa infection (white arrows)." (PMID 32243839, 2020). "To fate map the NPCs following either a knockdown or knockout of DCX in vivo, we utilized a retrovirus approach to infect and track the maturation of the dividing NPCs that develop into granule neurons, expressing NeuN by 30 days post infection (dpi)." (PMID 26793044, 2015). "Upon administration of rAAV, many of the DCX+ neurons are postmitotic and initially spared but are not replenished by the ablated Tbr2+ population, explaining the delayed and progressive loss of the DCX+ pool in response to rAAV infection." (PMID 34259630, 2021). "Indeed, following injection of a control retrovirus (DsRed only), virtually none of the DSRED+ transduced cells expressed the neuronal markers DCX and/or NEUN (<2%) or exhibited GC morphology at 4 dpi or 6 weeks post-infection (wpi)." (PMID 34592167, 2021). "The increased neuronal death observed in aged animals was accompanied by a decrease in neurogenesis, as aged animals showed reduced doublecortin (DCX) staining in the DG compared to adult animals, regardless of infection status." (PMID 39550693, 2025). "We next examined the intermediate DCX+ progenitor cells in the dorsal SVZ and no changes in the area occupied by these cells were produced by TMEV infection." (PMID 32192522, 2020). "At 3 days post infection (dpi), the vast majority of the transduced cells (GFP+) were positive for the astrocytic marker Aldh1l1 and negative for the neuronal markers NeuN and DCX." (PMID 33827819, 2021).
neurodevelopmental disorder (10 papers, 2015 to 2025). A behavioral and cognitive disorder with onset during the developmental period that involves impaired or aberrant development of intellectual, motor, or social functions. "Our study uncovers a novel role of the E3 ubiquitin ligase adaptor KLHL15 as a negative regulator of DCX protein abundance and dendritogenesis and suggests possible mechanistic connections in X-linked neurodevelopmental disorders." (PMID 33199366, 2021). "DCX-inactivating mutations cause severe structural brain abnormalities, whereas the case for DCLK1 and DCLK2 as disease genes for neurodevelopmental disorders is currently circumstantial." (PMID 33199366, 2021). "Further studies involving animal models are required to investigate the interplay between KLHL15 and DCX proteins in the pathogenesis of neurodevelopmental disorders." (PMID 33199366, 2021). "Additional indirect evidence for the involvement of USP9X in neurodevelopmental disorders comes from its interaction with doublecortin (DCX)." (PMID 25672900, 2015). "The results showed that several DAPs were associated with DCX or GFAP, indicating that acetylation may have a significant impact on neurodevelopmental disorders during CIH." (PMID 38455734, 2024).
neurological disorders (9 papers, 2009 to 2024). "This evidence point toward catastrophic consequences as a result of DCX mutations, which range from mild to severe neurological disorders, suggesting that DCX play crucial roles in the formation and maintenance of a functional brain." (PMID 28701917, 2017). "Doublecortin binds to a distinct site on microtubules from that occupied by dynein or kinesin, and we identify a second set of missense mutations and variants associated with neurological disorders at the tubulin-doublecortin interface." (PMID 38064432, 2023). "Doublecortin (DCX) is a microtubule (MT)-associated protein that regulates MT structure and function during neuronal development and mutations in DCX lead to a spectrum of neurological disorders." (PMID 35485925, 2022). "In this review, we will summarize current features of the neuronal MAP DCX, its expression in neurons and other tissues of various species, its roles in neurological disorders as well as its importance in cell proliferation during neurogenesis." (PMID 28701917, 2017).
neurodegenerative disease (1 paper, 2019). A disorder of the central nervous system characterized by gradual and progressive loss of neural tissue and neurologic function. "Depending on its cofactor, CDK5 in the brain phosphorylates targets involved in neurodegenerative diseases (e.g. Tau, MAP1B), neuronal migration (e.g. DCX), and synaptic signaling (e.g. Cav2.2, Dynamin1, NR2A, DARPP-32)." (PMID 31687929, 2019).
prostate (1 paper, 2022). "Mauffrey and colleagues reported that doublecortin (DCX)-positive neural progenitors from the central nervous system infiltrated prostate primary tumors and metastases." (PMID 36077804, 2022).
DCX also shares sentences with these, for which no sentence is quoted: amyloid (3 papers); tuberous sclerosis (3); atypical Rett syndrome (2); brain disease (2); heterotopia (2); Huntington disease (2); Miller-Dieker syndrome (2); psychiatric disorder (2); X-linked intellectual disability (2); adenoma (1); alcohol addiction (1); alcohol dependence (1); arteriosclerosis (1); arteriosclerotic cardiovascular disease (1); atherosclerosis (1); autism spectrum disorder (1); B cell deficiency (1); Beckwith-Wiedemann syndrome (1); Brain atrophy (1); brain inflammation (1); cervical cancer (1); CNS tumors (1); cognitive disorder (1); congenital heart disease (1); congestive heart failure (1); coronary artery disease (1); COVID-19 (1); delirium (1); dementia (1); Dent disease (1).
A further 36 diseases each share a sentence with DCX in 1 paper.